STK11 (serine/threonine kinase 11)
Diseases named in the same sentence as STK11 in open-access papers (continued):
Sharing a sentence is not in itself a finding about the gene and the disease.
ovarian carcinoma (42 papers, 1999 to 2025). A malignant neoplasm originating from the surface ovarian epithelium. "Among the dependencies associated with a kinase-substrate interaction, we found that mutation of STK11 (LKB1) in ovarian cancer models was associated with an increased dependency upon MARK2 (p = 2 × 10−3), an LKB1 substrate." (PMID 26947069, 2016). "In contrast, we clearly demonstrate that the majority of EOC solid tumour specimens, primary ascites-derived cells and established ovarian cancer cell lines retain detectable LKB1 protein expression since almost all serous ovarian cancers retain at least one STK11 allele." (PMID 26068970, 2015). "Among the four cases of patients with ovarian cancer, we found a Pathogenic variant in RAD51C, 2 VUSs, respectively in ATM and RAD50 genes, and a Likely-benign variant in STK11." (PMID 34299313, 2021). "Significant deletions were observed in regions such as 5q11-13, frequently reported as loss of heterozygosity (LOH) in ovarian cancer, 8p23 encoding DBC1 (deleted in breast cancer 1 gene), 10p24 harboring PTEN, 16q24 encoding CDH1 (E-cadherin) and FANCA, and 19q13.3 encompassing STK11 (LKB1)." (PMID 40953111, 2025). "Therefore, despite single allele loss of STK11, LKB1 protein expression is maintained in metastatic ovarian cancer cells and may in fact serve an important function in late-stage disease." (PMID 26068970, 2015). "We transfected SkOV3, OVCAR8 and iOvCa147-E2 ovarian cancer cell lines with pooled siRNAs against PRKAA1 (AMPKα1) and STK11 (LKB1)." (PMID 26068970, 2015). "Considering only the NCCN-recommended ovarian cancer screening genes, it was noticed that no mutations were detected in the recommended EPCAM and STK11 genes." (PMID 38817903, 2024).
squamous cell carcinoma (41 papers, 2008 to 2026). A carcinoma arising from squamous epithelial cells. "Similarly, preclinical studies using KRAS G12C-mutant mouse models with STK11/LKB1 deletions have identified adenocarcinoma-to-squamous cell carcinoma transformation (AST) as a pathological feature linked to primary drug resistance." (PMID 40303413, 2025). "Interestingly, these subtypes are enriched in STK11/LKB1 mutations (subtype 4) and squamous cell carcinomas (subtype 6), which are both features of the KL model." (PMID 35941104, 2022). "However, we identified a higher rate of STK11 mutations in squamous cell carcinoma in the Inuit tumors than previously reported and this will need to be confirmed with further studies." (PMID 35621648, 2022). "The clinical significance of LKB1 loss in cancer plasticity is that KRASG12D and STK11 co-mutations have a squamous cell carcinoma gene signature linked to resistance against KRAS inhibitors." (PMID 39735555, 2025). "PTEN loss is common in squamous cell cancers (SCC) and small cell lung cancer, whereas STK11 is often found mutated in adenocarcinoma." (PMID 33652656, 2021). "Transcriptomic and genomic analysis on pre-treatment biopsies from patients in the KRYSTAL-1 trial revealed that patients presenting a baseline high expression of squamous cell carcinoma-related genes and STK11/LKB1 co-mutations had a shorter treatment duration with adagrasib." (PMID 39301544, 2024). "On the other hand, squamous cell carcinoma cases of the cervix were entirely HPV-associated and mutations occurred in the PIK3CA (60%) gene, whereas mucinous carcinomas were HPV-independent and mostly exhibited alterations in the STK11 gene." (PMID 36010253, 2022). "Somatic mutations of STK11/LKB1 are found in several malignancies including NSCLC where they may be present in up to 30% of the patients, more frequently in adenocarcinoma than in squamous cell carcinoma." (PMID 32365882, 2020). "Stk11 deletion under progenitor cell-type-restricted adenoviral Cre revealed that CC10+ cells are the predominant progenitors of adenosquamous and squamous carcinoma while SPC+ cells only develop typical LUAD." (PMID 35406531, 2022). "Although, LCNECs also harbored alterations commonly observed in adenocarcinomas and squamous cell carcinomas, even LCNECs with such alterations in KEAP1 or STK11 were primarily found in transcriptional subclasses shared with SCLC." (PMID 29535388, 2018).
cardiac hypertrophy (37 papers, 2014 to 2026). "SIRT2 protects against angiotensin II-induced cardiac hypertrophy by deacetylating STK11 and activating AMPK signaling." (PMID 38355681, 2024). "Conversely, miR-451 exacerbates high-fat diet-induced cardiac hypertrophy and lipotoxicity in mouse cardiomyocytes by suppressing the serine/threonine kinase 11 (LKB1)/AMPK signaling pathway." (PMID 30174600, 2018). "Interestingly, the study on STK11 knock-out mice showed that the mice exhibited cardiac hypertrophy and dysfunction with a decrease in capillary density of both atria and ventricles, which was consistent with significant lower mRNA and protein levels of vascular endothelial growth factor." (PMID 28349069, 2017).
endometrial cancer (37 papers, 2011 to 2025). Primary or metastatic malignant neoplasm involving the endometrium (mucous membrane that lines the endometrial cavity). "Our data implicating a tumor suppressor role of STK11 in EC are in agreement with previous studies involving cell lines and animal models, where STK11 deficiency was strongly associated with highly invasive phenotype of endometrial carcinoma cells." (PMID 36140779, 2022). "In endometrial cancer, STK11 inactivation enhances MCP-1/CCL2 expression, which increases immune cell recruitment." (PMID 41051525, 2025). "Endometrial cancer was described in individuals with STK11 alterations." (PMID 39408606, 2024). "STK11 and FLT4 genes were covered by CNVs in the relative of MPT21.2, who presented endometrial cancer." (PMID 39408606, 2024). "STK11 and ATM appeared as risk modifiers in our screen and are frequently mutated somatically but not in endometrial cancer (COSMIC database)." (PMID 26517685, 2015).
Obesity (33 papers, 2012 to 2026). Accumulation of substantial excess body fat. "STK11 encodes LKB1, which signals through AMPK to negatively regulate lipid, cholesterol, and glucose metabolism; metabolic changes associated with obesity downregulate the LKB1-AMPK signaling axis, contributing to cancer risk." (PMID 37452870, 2023).
diabetes (32 papers, 2012 to 2026). "Based on the previous research on STK11 and diabetes, we aimed to investigate the distributive characteristic of STK11 rs2075604 polymorphism and the potential influence of STK11 rs2075604 polymorphism on metformin efficacy among Chinese T2DM patients." (PMID 28775741, 2017). "STK11 is also considered a tumor suppressor in prostate cancer and is targeted by the diabetes drug metformin which has been shown to have anti-cancer activity." (PMID 37415738, 2023). "In this study, we found that there was an association between SNPs at STK11 locus and individual susceptibility to CAD in the Chinese type 2 diabetes mellitus (DM) patients." (PMID 28349069, 2017). "Likewise, some early connections of CDH1 (cell adhesion) and STK11 (metabolic LKB1 regulator) with type 2 diabetes mellitus establish common pathways for both diseases." (PMID 40989682, 2025).
gastric cancer (32 papers, 2003 to 2025). A primary or metastatic malignant neoplasm involving the stomach. "Particularly, cadonilimab offers new therapeutic opportunities in traditionally immunotherapy-resistant populations (e.g., HER2-positive, STK11-mutated, and microsatellite stable gastric cancer)." (PMID 40861473, 2025). "A novel STK11 mutation, F354L, was also observed in six patients, all with intestinal type gastric cancers." (PMID 31941061, 2020). "Decreased STK11 expression is associated with EMT in gastric cancer and hence poor prognosis." (PMID 37506141, 2023). "Based on the family history of gastric lesions reported in the examined Italian family, we sought to correlate the location of STK11 nonsense and frameshift mutations with gastric cancer susceptibility by performing a meta-analysis of published studies comprising relevant clinical data." (PMID 35224145, 2022). "The patient with the frameshift mutation in STK11 gene developed aggressive gastric cancer." (PMID 19615099, 2009). "Moreover, we observed a new case of aggressive gastric cancer in a young patient with a frameshift mutation of STK11 gene." (PMID 19615099, 2009). "All but the one case of stomach cancer was associated with LKB1/STK11 mutations." (PMID 12865922, 2003). "Successful treatment outcomes have been reported in patients with MSI-H gastric cancer, HER2-amplified gastric cancer, STK11-mutant NSCLC, PD-1-resistant nasopharyngeal carcinoma, multiple primary malignancies, and super-aged populations." (PMID 40861473, 2025). "In light of this finding, we performed a meta-analysis to ascertain whether STK11 nonsense and frameshift germline mutations may affect gastric cancer (GC) susceptibility in PJS patients based on their location." (PMID 35224145, 2022). "These potentially new gastric cancer driver genes, as well as genes with high nonclonal mutation frequency, such as STK11, GPS2, NDUFB9, and AXIN2, represent good candidates for inclusion in future studies of gastric tumorigenesis." (PMID 36970058, 2022). "Notably, our patient cohort is all Korean advanced gastric cancer, and nearly 30% of the STK11-altered TCGA samples are from Asian origin." (PMID 32158697, 2020). "Gastric cancer in the pediatric age group is rare and usually associated with recognized polyposis germline mutations (APC for familial adenomatosis polyposis coli and STK11 for Peutz–Jeghers syndrome) and E-cadherin mutations in patients as young as 15 years old or younger." (PMID 37754493, 2023).
gastric cancer (continued). "Larger Asian series from advanced gastric cancer patients will be needed to examine whether or not STK11 alteration frequencies differ between Western and Asian populations." (PMID 32158697, 2020). "Owing to small sample size we cannot draw further conclusions, though examining larger Asian cohorts may be warranted to examine whether or not STK11 differs between Western and Asian gastric cancers." (PMID 32158697, 2020).
Lynch syndrome (31 papers, 2013 to 2025). An autosomal dominant hereditary neoplastic syndrome characterized by the development of colorectal carcinoma and a high risk of developing endometrial carcinoma, gastric carcinoma, ovarian carcinoma, renal pelvis carcinoma, and small intestinal carcinoma. "High risk consisted of >1 first‐degree relatives with PC or PC‐associated mutations (i.e. BRCA2, Lynch Syndrome, Familial Atypical Multiple Mole Melanoma Syndrome, STK11, or PALB2)." (PMID 33319059, 2020). "No pathogenic variants were observed in BRCA1, STK11, CDKN2A, APC, PRSS1, or those genes associated with Lynch syndrome." (PMID 39594734, 2024).
prostate carcinoma (31 papers, 2012 to 2025). A carcinoma that arises from epithelial cells of the prostate gland. "However, it induces apoptosis in STK11‐deficient prostate cancer cells." (PMID 36760166, 2023). "Another recent report demonstrates that the tumor suppressor gene LBK1 (STK11) is lost in AR-independent prostate cancer subtypes." (PMID 40454483, 2025). "However, TPD52 upregulation in drug resistant-prostate cancer cells leads to STK11 and AMPK downregulation and subsequent inhibition of autophagy." (PMID 35317831, 2022). "Liver kinase B1 (LKB1/STK11) is a key tumor suppressor that regulates cellular metabolism, epigenetic states, and multiple signaling pathways in prostate cancer (PCa)." (PMID 40874022, 2025). "Exposing prostate cancer cells to docetaxel inhibits TPD52 and STK11/LKB1 (serine/threonine kinase 11) interaction to promote STK11 expression." (PMID 35317831, 2022). "So that, drug‐mediated inactivation of MAPK14 does not affect the survival of STK11‐positive prostate cancer cells due to the activation of the AMPK‐dependent autophagic pathway." (PMID 36760166, 2023).
colon carcinoma (30 papers, 2004 to 2025). "Taken together, silencing of STK11/LKB1 in this colon cancer line was associated with local and systemic elevation of LIF, another IL-6 family pro-inflammatory cytokine associated with CC development in colon cancer murine models." (PMID 37092555, 2023). "Germline mutation of STK11 was identified in one patient with a family history of colon cancer." (PMID 35709138, 2022). "A patient in his 30s (case 25), referred for hereditary colon cancer testing due to polyps, initially underwent CMA followed by qPCR confirmation, which identified a pathogenic deletion of STK11 (NM_000455.5) exons 2-5." (PMID 41210374, 2025). "Several genes in the backbone of the CHIEF pathway were associated with survival, including PIK3CA for colon cancer and PRKAG2, STK11, and TSC2 for rectal cancer." (PMID 25541970, 2014). "Interactions between the STK11 (LKB1)-AMPK pathway and the MAPK3/1 pathway in human cancer cells including colon cancer cells have been documented." (PMID 20808308, 2010). "LKB1/STK11, however, is rarely involved in sporadic colon cancer cases and at most 33% of NSCLC cases, leading us to consider the role of MBD3 as an alternative tumour-suppressor gene on this location." (PMID 15138480, 2004).
Hepatic steatosis (25 papers, 2011 to 2025). Steatosis is a term used to denote lipid accumulation within hepatocytes. "The stk11 mutants show hepatic glycogen depletion and hepatic steatosis 7 dpf, a point in development when the wild-type siblings show adequate glycogen content and no steatosis." (PMID 22678663, 2012). "Nevertheless, in contrast to our work with the AB × Singapore × WIK wild-type siblings of rmn mutants, the TL × AB (×München, possibly) wild-type siblings of stk11 mutants do develop hepatic steatosis in the never fed state by 11 dpf." (PMID 22678663, 2012).
Cowden syndrome (21 papers, 2008 to 2025). "Additionally, the Hamartomatous polyposis syndromes that englobe the syndrome of PeutzJeghers (PJS), the syndrome of Juvenile Polyposis (JPS), and the syndrome of Cowden are autosomal dominant syndromes caused by germline mutations in STK11/LKB1, BMPR1A/SMAD4, and PTEN, respectively." (PMID 34326875, 2021). "There may be a number of different genetic drivers which can lead to the creation of pre-cancerous niches in Cowden Syndrome (associated with the PTEN tumour suppressor), Peutz–Jeghers Syndrome (associated with STK11/LKB1 gene) and other such conditions." (PMID 26082798, 2015).
type 2 diabetes (18 papers, 2010 to 2025). "Genetic variability at STK11 locus is associated with CAD risk in type 2 diabetes in the Chinese population." (PMID 28349069, 2017). "For the STK11 gene, genetic variability at rs12977689 has been linked to an increased risk of coronary artery disease (CAD) in type 2 diabetes patients." (PMID 37607939, 2023). "To test the hypothesis, we carried out a case-control study to assess the potential effect of STK11 gene on CAD in Chinese Han population with type 2 diabetes." (PMID 28349069, 2017).
lung squamous cell carcinoma (16 papers, 2014 to 2026). "We previously reported that conditional biallelic deletion of the genes Pten and Lkb1 (a.k.a Stk11) with inhaled adeno-Cre virus leads to lung squamous cell carcinoma." (PMID 38265267, 2024).